RHOB (ras homolog family member B)
Description:
Mediates apoptosis in neoplastically transformed cells after DNA damage. Not essential for development but affects cell adhesion and growth factor signaling in transformed cells. Plays a negative role in tumorigenesis as deletion causes tumor formation. Involved in intracellular protein trafficking of a number of proteins. Targets PKN1 to endosomes and is involved in trafficking of the EGF receptor from late endosomes to lysosomes. Also required for stability and nuclear trafficking of AKT1/AKT which promotes endothelial cell survival during vascular development. Serves as a microtubule-dependent signal that is required for the myosin contractile ring formation during cell cycle cytokinesis. Required for genotoxic stress-induced cell death in breast cancer cells.
Synonyms: ARH6; ARHB; RHOH6; MST081; MSTP081
Tractability: Small molecule: a structure with a bound ligand is known. Antibody: its Gene Ontology location is reachable by antibodies, with high confidence; UniProt places it where antibodies can reach, with medium confidence. PROTAC: ubiquitination databases record sites on it; its protein half-life has been measured.
Gene: Protein-coding gene on chromosome 2 (20,447,074 to 20,449,440, forward strand). Ensembl gene ENSG00000143878.
Subcellular location: Late endosome membrane; Cell membrane; Nucleus; Cleavage furrow
Pathways (Reactome):
Signal Transduction: G alpha (12/13) signalling events; RHO GTPases Activate Formins; RHO GTPases Activate ROCKs; RHO GTPases Activate Rhotekin and Rhophilins; RHO GTPases activate CIT; RHO GTPases activate PKNs; RHOB GTPase cycle
Developmental Biology: Sema4D induced cell migration and growth-cone collapse
Hemostasis: GPVI-mediated activation cascade
Gene Ontology:
Molecular function: protein binding; GTP binding; GTPase activity; G protein activity; GDP binding
Biological process: cellular response to hydrogen peroxide; cellular response to ionizing radiation; endosome to lysosome transport; endothelial tube morphogenesis; mitotic cytokinesis; negative regulation of cell migration; negative regulation of establishment of endothelial barrier; positive regulation of apoptotic process; positive regulation of endothelial cell migration; regulation of cell migration; actin filament organization; apoptotic process; cell adhesion; negative regulation of cell cycle; positive regulation of angiogenesis; Rho protein signal transduction; positive regulation of cell migration; regulation of modification of postsynaptic structure; small GTPase-mediated signal transduction
Cellular component: cleavage furrow; endosome membrane; extracellular exosome; focal adhesion; plasma membrane; cytosol; nucleus; early endosome; late endosome; late endosome membrane; membrane; Schaffer collateral - CA1 synapse; synapse
Genetic constraint (gnomAD): Loss-of-function variants: 6 observed, 13.74 expected, observed/expected ratio (o/e) 0.44, 90% interval 0.24 to 0.86. The synonymous counts are far from expectation, so gnomAD's model fits this gene poorly and the ratio says little. Missense variants: 142 observed, 300.37 expected, observed/expected ratio (o/e) 0.47, 90% interval 0.41 to 0.54. Synonymous variants: 168 observed, 131.97 expected, observed/expected ratio (o/e) 1.27, 90% interval 1.12 to 1.45.
Homologues: Orthologues: dog RHOB (100% identical), mouse Rhob (100% identical), pig RHOB (100% identical), rabbit RHOB (100% identical), rat Rhob (100% identical), chimpanzee RHOB (98% identical), tropical clawed frog rhob (91% identical), Drosophila melanogaster Rho1 (80% identical). Paralogues in human: RHOA (84% identical), RHOC (84% identical), RAC1 (53% identical), RAC2 (53% identical), RAC3 (53% identical), RHOG (53% identical), RHOQ (50% identical), RHOD (49% identical), CDC42 (49% identical), RHOJ (47% identical), RHOF (47% identical), RND3 (47% identical), and 10 more.
Diseases named in the same sentence as RHOB in open-access papers:
RHOB is named in the same sentence as 118 diseases in open-access papers, as found by Europe PMC text mining. Sharing a sentence is not in itself a finding about the gene and the disease. The quoted sentences say what the papers report.
breast carcinoma (41 papers, 2005 to 2024). "Our result indicated that the depletion of CUL3 or KCTD10 caused the accumulation of RhoB protein in HER2-positive breast cancer cells." (PMID 34187934, 2021). "We showed that strong expression of RhoA and low expression of RhoB was associated with the basal-like subtype of breast cancer." (PMID 33162807, 2020). "DLC3 depletion in breast cancer cells also caused aberrant Rab4-dependent matrix metalloproteinase recycling and invadopodia matrix degradation in a RhoB- and actin-dependent manner." (PMID 31766364, 2019). "As previously shown, loss of oncogenic miR-21, acting to repress RHOB expression, is associated with an elevation of RHOB in hepatocellular carcinoma and breast cancer cells." (PMID 24466274, 2014). "Although the tumor suppressor function of RhoB has been documented in many human cancers, RhoB overexpression was suggested to be associated with tumor progression in breast cancers." (PMID 23339407, 2013). "In human breast cancer cell lines, RhoB attenuation was associated with reduced expression of both ERα and PR, whereas elevation of RhoB was found to be associated with ERα overexpression." (PMID 23339407, 2013). "Overexpression of RhoB in breast cancer was related to tumor progression, whereas the loss of RhoB expression in advanced lung cancer suggested that it may play a tumor‐suppressing role." (PMID 36710485, 2023). "However, in HER2-positive breast cancer cells Rac1 activity could also be increased due to Cullin3-KCTD10-mediated loss of RhoB." (PMID 34136490, 2021). "Some investigators found that RHOB expression was upregulated after treatment with atorvastatin, implying the potential application of RHOB as a target for tumor suppressor gene therapy in breast cancer." (PMID 39376611, 2024). "A major consequence of RHOB regulation is that it differentially affects the proliferation of breast cancer cell lines." (PMID 39376611, 2024). "The lncRNA DUXAP8, transcribed from a pseudogene, modulates both the P3K/AKT/mTOR pathway and the EZH2-E-cadherin/RHOB pathways to exert its role in inducing breast cancer radioresistance." (PMID 39346726, 2024). "After the transfection of siEmi1, the mRNA levels of proliferation-related molecules PDCD-4, FasL, PTEN and RhoB in breast cancer cell strains were significantly reduced." (PMID 38041032, 2023). "The PDCD-4, FasL, PTEN and RhoB genes have tumour-suppressing effects, and their expression is significantly reduced in malignant tumours, such as breast cancer and lung cancer." (PMID 38041032, 2023). "This confirms that Emi1 KD can regulate the proliferation-related proteins PDCD-4, FasL, PTEN and RhoB in breast cancer cells." (PMID 38041032, 2023). "Overall, these results suggest that the SMAD3-dependent gene signature is present in hypoxic tumors and that VIM and ITGB2 are better predictors of metastasis or cancer recurrence in lung carcinoma and breast cancer than RHOB." (PMID 35681731, 2022). "RhoB stability is not only regulated by Cullin3 in HER2-positive breast cancer but also in hepatocellular carcinoma." (PMID 34136490, 2021). "Taken together, it is likely that the regulation of EGFR phosphorylation through PTPRH activation and RhoB degradation by the CUL3/KCTD10 E3 complex is conserved in HER2/EGFR-double positive breast cancer cells." (PMID 34187934, 2021). "For HER2/EGFR double-positive breast cancer cells, our present study suggests that RhoB functions as a tumor suppressor because its constitutive degradation by the CUL3/KCTD10 E3 complex is essential for cell proliferation of SKBR-3 cells." (PMID 34187934, 2021). "We thus examined if the expression level of RhoB correlates with the prognosis of human HER2/EGFR-double positive breast cancer patients using the Molecular Taxonomy of Breast Cancer International Consortium (METABRIC) database." (PMID 34187934, 2021).
breast carcinoma (continued). "We also found that low mRNA expression of RhoB significantly correlated with poor prognosis for HER2-positive/EGFRhigh breast cancer patients (P = 0.0053, high: n = 54, low: n = 30)." (PMID 34187934, 2021). "In contrast, high mRNA expression of RhoB significantly correlated with poor prognosis for HER2-positive/EGFRlow breast cancer patients (P < 0.0001, high: n = 14, low: n = 96)." (PMID 34187934, 2021). "Using a cohort of 106 breast tumors from the Jean Perrin hospital and data from the TCGA project, we found that a high RhoA/RhoB expression ratio was characteristic of triple negative/basal-like breast cancers." (PMID 33162807, 2020). "In contrast to RhoA and RhoB, research is more conclusive on the enhancing effects of RhoC on breast cancer migration and invasion." (PMID 32992837, 2020). "In this regard, the expression of geranylgeranylated RhoB, one of the major prenyl modifications critical for Rho GTPase function, was found to promote apoptosis of breast cancer cells." (PMID 32992837, 2020). "To confirm these findings, we looked at the expression of RhoA and RhoB in basal-like breast cancer tumors." (PMID 33162807, 2020). "Among the four types, the expression level of RhoB was the highest in luminal A breast cancer tissues and the expression level of RhoB was the lowest in basal-like breast cancer tissues." (PMID 31011573, 2019). "The results showed that, after treatment with ATO in breast cancer cells, the mRNA and protein levels of RhoB and PTEN were significantly upregulated, while the protein levels of p-AKT were significantly downregulated." (PMID 31011573, 2019). "We then used online database Kaplan-Meier Plotter to evaluate the expression levels of RhoB of relapse-free survival (RFS) of breast cancer patients." (PMID 31011573, 2019). "By analyzing the data from TCGA database, we found that RhoB expression was significantly downregulated in breast cancer tissues." (PMID 31011573, 2019). "The database classified breast cancer patients into high expression group (red line) and low expression group (black line) based on the median RhoB expression level." (PMID 31011573, 2019). "The exact mechanism of ATO's carcinostatic effects in breast cancer is related to downregulating PTEN/AKT pathway via promoting RhoB." (PMID 31011573, 2019). "The expression of RhoB in mRNA and protein level was upregulated in statin-treated breast cancer cells and downregulated in cancer tissues." (PMID 31011573, 2019). "Subsequently we compared the differences of RhoB expression levels in breast cancer tissues with different PAM50 types." (PMID 31011573, 2019). "A window-of-opportunity phase II trial revealed that 21 genes were upregulated including RhoB in breast cancer tissues after the patients treated with ATO." (PMID 31011573, 2019). "Verification in human breast cancer cell lines demonstrates that there is a signal pathway crossover between estrogen receptor alpha and RhoB." (PMID 31011573, 2019). "The expression level of Ras homolog family member B (RhoB) in breast cancer cells was found to be upregulated after being treated with ATO." (PMID 31011573, 2019). "Our study confirms that RhoB inhibits breast cancer proliferation, invasion, and EMT by inhibiting PTEN/AKT signaling pathway." (PMID 31011573, 2019). "Subsequently, we examined changes in RhoB protein and mRNA levels in breast cancer cells and animal breast tumor tissues after atorvastatin treatment." (PMID 31011573, 2019). "In this study, we intend to study the inhibitory effects of ATO on breast cancer cells and related mechanisms and secondly to evaluate the role of RhoB in breast cancer." (PMID 31011573, 2019). "Distribution of RhoB in different breast cancer tissues and its influence on prognosis were analyzed using the data from TCGA or GEO databases." (PMID 31011573, 2019). "Most importantly, Arf6 or RhoB depletion enhanced the c-Met-dependent 3D migration of invasive breast cancer cells." (PMID 31766364, 2019).
breast carcinoma (continued). "Our findings complement the mechanism by which ATO inhibits breast cancer and demonstrates the potential of RhoB to become a biomarker for breast cancer." (PMID 31011573, 2019). "To assess the expression of RhoB in breast cancer and normal tissues, we analyzed the expression levels and related clinical data of RhoB in tissues derived from the TCGA database using the Metabolic gEne RApid Visualizer online tool." (PMID 31011573, 2019). "In a phase II clinical trial, researchers found that RhoB expression increased in tissue samples from breast cancer patients after treatment of ATO." (PMID 31011573, 2019). "Our study also demonstrates the potential applicability of RhoB as a therapeutic target for breast cancer." (PMID 31011573, 2019). "Low expression of RhoB links with poor prognosis in patients with breast cancer (HR = 0.74[0.66–0.83], p =7e−8, log-rank test)." (PMID 31011573, 2019). "This study further supports the important role of ATO in the adjuvant treatment of breast cancer and suggests that RhoB has the potential to become a new biomarker for breast cancer." (PMID 31011573, 2019). "The results showed that the mRNA and protein expression levels of RhoB in breast cancer tissues were lower than those in adjacent tissues." (PMID 31011573, 2019). "Here, we demonstrated that, by contrast to lung and breast cancer cells, RHOB downregulation decreases AKT phosphorylation in melanoma, similarly to endothelial cells." (PMID 26098773, 2015). "In contrast to other cancer models, RhoB is critical for the proliferation of ERα-expressing breast cancer cells, suggesting its role as a positive regulator in this model." (PMID 23339407, 2013). "Using the Oncomine microarray database, a correlation between RhoB and either ERα or PR expression was documented in datasets from 19 breast cancer studies." (PMID 23339407, 2013). "A major consequence of RhoB modulation was that RhoB differentially regulated the proliferation of breast cancer cell lines." (PMID 23339407, 2013). "First, in human breast cancer tissues we clearly showed a strong correlation between RhoB expression and the expression of ERα and PR." (PMID 23339407, 2013). "Our new findings shed light on the role of RhoB in tumorigenesis involving a dual effect conferred by cellular context with a potential pro-oncogenic function in hormone-dependent breast cancer cells." (PMID 23339407, 2013). "Taken together, our findings offer evidence that in human breast cancer RhoB acts as a positive function to promote expression of ERα and PR in a manner correlated with cell proliferation." (PMID 23339407, 2013). "Using cellular and human breast tumor analytical approaches, we have shown a positive crosstalk between RhoB and ERα expression and the critical role of RhoB in regulation of the proliferation of ERα-expressing breast cancer cells." (PMID 23339407, 2013). "ECT2 has recently been reported to be involved with mechanisms for activating RhoB after genotoxic stress, thereby facilitating cell death after treatment with DNA damaging agents in Breast Cancer." (PMID 22952662, 2012). "High expression of RhoB in testicular cancer and breast cancer was found to be related to tumor progression, but whether it plays a tumor‐promoting or tumor‐suppressing role in colon cancer remains controversial." (PMID 36710485, 2023). "Studies have reported that the programmed cell death receptor 4 (PDCD-4), fatty acid synthase ligand (FasL), PTEN and RhoB genes are related to the proliferative regulation of breast cancer cells and that Maspin, TIMP3 and RECK genes are related to the invasion regulation of breast cancer cells." (PMID 38041032, 2023). "The proteins encoded by the PDCD-4, FasL, PTEN and RhoB genes are related to the regulation of breast cancer cell proliferation, and the proteins encoded by the Maspin, TIMP3 and RECK genes are related to the regulation of breast cancer cell invasion." (PMID 38041032, 2023).
breast carcinoma (continued). "In breast cancer, loss of RhoB had negatively (no) effect on cancer metastasis, RhoB overexpression result in decreased cancer metastasis to the liver, lungs, and lymph nodes of mouse." (PMID 33761933, 2021). "Finally, we asked if there was a clinical correlation between primary GBM and breast cancers with PTEN wt or PTEN splice or other mutations and RHOB expression using The Cancer Genome Atlas (TCGA)." (PMID 34680293, 2021). "Similar to RhoA, RhoB effects on breast cancer migration and invasion are complex." (PMID 32992837, 2020). "As RhoB is expressed at very lower levels in basal-like breast cancer cell lines, we hypothesized that Rhosin treatment would have the same effect as RhoA siRNA." (PMID 33162807, 2020). "In breast cancer, RhoB expression has been found to be inversely related to tumor progression." (PMID 33162807, 2020). "Nevertheless, we showed that basal-like breast cancer cells express RhoB protein at lower levels." (PMID 33162807, 2020). "This suggests that the reversion of the oncogenic RhoC-mediated phenotype in breast cancer may be mediated by RhoB, and that RhoB and RhoC may have antagonistic roles in TNBC cell lines." (PMID 32992837, 2020). "A more mechanistic study determined that at least in estrogen receptor (ER)-positive breast cancer, RhoB drives proliferation by modulating the expression of the ER, leading to changes in the cellular response to estrogen, in multiple ER-positive breast cancer cell lines." (PMID 32992837, 2020). "In the present study, we analyzed the data in the database and found that, in different PAM50 subtype of breast cancer, RhoB mRNA expression was highest in the subtype with lowest malignancy (luminal A), while RhoB mRNA was the lowest in the subtype with highest malignancy (basal-like)." (PMID 31011573, 2019). "Compared with normal breast tissues, RhoB expressions were lower in breast cancer tissues." (PMID 31011573, 2019). "To detect the effect of RhoB on PTEN/AKT signaling pathway in breast cancer cells, we respectively used Western blot to detect changes in the expression levels of PTEN/AKT signaling pathway-related protein AKT, p-AKT, and PTEN after overexpression and knockdown of RhoB in MDA-MB-231 cells and MCF-7." (PMID 31011573, 2019). "The results showed that ATO upregulated RhoB mRNA and protein expression in breast cancer cells." (PMID 31011573, 2019). "Similarly, shRNA-mediated reduction of RhoB in MDA-MB-231 breast cancer cells displayed a hyperproliferative phenotype, which was actually associated with decreased invasion into a matrigel matrix." (PMID 29385717, 2018). "The RhoB is one of the downregulated GTPases in breast cancer and invasive carcinomas of the head and neck; accordingly, we found a decreased RhoB protein expression in the pancreatic cancer cell lines BxPC3 and PANC-1, as compared to non-cancerous pancreatic cell line hTERT-HPNE." (PMID 27832197, 2016). "To test whether the influence of RhoB silencing on transduction by Ad5-based vectors might be a general rule, we performed the same experiment in a human breast carcinoma cell line, MDA-MB-435S." (PMID 24466204, 2014). "A major goal of the present study was therefore to determine the involvement of RhoB in hormone-dependent breast cancers and to investigate hypothesized crosstalks between RhoB and ERα signaling." (PMID 23339407, 2013). "RhoA, RhoB and Cdc42 protein expression was detected in all breast cancer cases." (PMID 23420497, 2013).